VDAC1 (voltage dependent anion channel 1)
Diseases named in the same sentence as VDAC1 in open-access papers (continued):
Sharing a sentence is not in itself a finding about the gene and the disease.
tumor (continued). "Tumour treatment with si-RNA against human (h) VDAC1 resulted in rewired metabolism, inhibited cell proliferation, epithelial-mesenchymal transition (EMT), invasion, angiogenesis and stemness, while leading to tumour cell differentiation into neuronal-like cells." (PMID 30544833, 2018). "The tumor aggressiveness in these patients could be the result of the combination of a switch to EMT process activation, re-expression or maintenance of the primary cilium, together with a decrease in VDAC1 and LGMN expression and thus the disappearance of the cleaved form of VDAC1." (PMID 32194829, 2020). "Previous studies have reported that PK5 prefers to suppress tumor cells under hypoxic but not normoxic conditions because of higher expression of its ligands GRP78 and VDAC1 on tumor cells under hypoxic conditions." (PMID 36793021, 2023). "The tumorigenesis and tumor progression of HCC are complex processes, and the specific mechanism by which VDAC1 alters HCC metabolism has not yet been elucidated." (PMID 35686107, 2022). "An additional novel group, in which the primary cilium is re-expressed or maintained, lacked VDAC1-ΔC yet maintained glycolysis, a signature of epithelial-mesenchymal transition (EMT) and more aggressive tumor progression, but was independent to VHL." (PMID 32194829, 2020). "We suggest that the mechanism by which IA could be leading to the death of tumor cells is through its binding to HKII, which, in turn, no longer joins to VDAC1, thus allowing the resumption of apoptosis." (PMID 37569780, 2023).
neurodegenerative disease (27 papers, 2012 to 2025). A disorder of the central nervous system characterized by gradual and progressive loss of neural tissue and neurologic function. "VDAC1 has also been associated with the pathological mechanisms involved in other neurodegenerative diseases, such as Huntington’s disease (HD), a neurodegenerative disorder caused by repeat expansions in the huntingtin (HTT) gene." (PMID 39858428, 2024). "In addition, proteins including SOD1, α-synuclein, and apoE, which all bind VDAC1 have been implicated in affecting intraneuronal Ca2+ in several neurodegenerative diseases." (PMID 33114780, 2020). "In conclusion, due to the influence of miRNAs on the expression level of VDAC-1, miRNAs seem to be a promising target for developing therapeutic approaches regarding different neurodegenerative diseases like AD." (PMID 40649921, 2025). "Third, VDAC1 is the physiological receptor of cytosolic enzymes, but also of misfolded proteins in several neurodegenerative diseases." (PMID 40223243, 2025). "On the other hand, elevated VDAC1 expression and subsequent oligomerization have been proposed to constitute a focal point in apoptotic signaling cascades, also in the context of neurodegenerative disease." (PMID 34942149, 2022). "High levels of VDAC1 have been demonstrated in brains of post-mortem AD patients, in AD-like transgenic mice, and in other neurodegenerative disease models." (PMID 36578022, 2022). "Lately, the interest for this channel has spanned into the neuroscience field with the successive findings of VDAC1 serving as the docking site for several neurodegenerative disease-related misfolded proteins." (PMID 31214047, 2019). "A common feature of neurodegenerative diseases is represented by the accumulation of misfolded protein and peptides upon the cytosolic surface of mitochondria or to the VDAC1." (PMID 29682501, 2018). "In this review, we examined the role of VDACs, particularly VDAC1 in mitochondria, in the physiology and pathophysiology of neoplastic and neurodegenerative diseases and cardiac IR injury." (PMID 28713289, 2017). "Specific examples of VDAC1 role in neoplastic and neurodegenerative diseases, and cardiac ischemia and reperfusion (IR) injury are presented." (PMID 28713289, 2017). "Finally, VDAC1 plays a pivotal role in mitochondrial dysfunction, as observed across various neurodegenerative diseases, including AD, PD, ALS, and others." (PMID 39858428, 2024). "Though other phosphorylation sites on VDAC1 have been identified and several of these sites have been implicated in cardiac and neurodegenerative diseases, their functional consequences have not been delineated." (PMID 34083717, 2021). "Very similar results were achieved by using DIDS analogs (H2DIDS, SITS, DPC) which successfully counteracted cisplatin- or selenite-induced apoptosis in SH-SY5Y cells (a cell line commonly used as model of neurodegenerative diseases), again by diminishing the oligomerization of VDAC1." (PMID 29682501, 2018). "Thus, VBIT-4 is a promising new VDAC1-based drug candidate for the treatment of AD, and it may effectively treat other neurodegenerative diseases." (PMID 36578022, 2022). "Only AD showed an involvement of pl-VDAC-1, while for all other neurodegenerative diseases, reports are not available so far." (PMID 40649921, 2025). "In addition, due to the proposed function of TSPO in apoptosis, potentially via its interactions with VDAC1, interfering with the TSPO-VDAC1 interaction can offer a target for the development of drugs directed at neurodegenerative diseases." (PMID 31288390, 2019). "An important property of the neurodegenerative diseases is the downregulated oxidative phosphorylation because of the dysfunctional brain mitochondria and the varied genes including UQCRC1, UQCR10, SDHB, ATP5B, ATP5C1, NFUFA1, and VDAC1." (PMID 29359159, 2017).
neurodegenerative disease (continued). "On these results, VDAC1 emerges as a crucial molecule in mitochondrial dysfunction in AD and as a promising pharmacological target for the development of new therapeutic avenues for this devastating neurodegenerative disease still without a cure." (PMID 40223243, 2025).
infection (23 papers, 2009 to 2025). The state of being infected such as from the introduction of a foreign agent such as serum, vaccine, antigenic substance or organism. "EV-A71 and FMDV infection induced mPTP opening, leading to VDAC1-dependent and Bak/Bax-independent mtDNA release." (PMID 36745686, 2023). "Mcu, Micu1, and Vdac1 were all significantly downregulated for both shRNAs 7 days after infection, on DIV 10, suggesting that their altered expression was due to a homeostatic mechanism rather than an off-target effect of either shRNA." (PMID 34942149, 2022). "For instance, a previously unreported neo-N terminus in VDAC1 (P1’ = Thr83) was altered in an infection- and T3S-dependent manner." (PMID 32487743, 2020). "VDAC1 was also involved in the infection of viruses, such as infectious bursal disease virus (IBDV)." (PMID 33329485, 2020). "Cytosolic cytochrome c appeared at 24 h pi and reached a peak at 36 h pi with a subsequent decrease at 48 h pi, while VDAC1 as mitochondrial protein marker remained in its subcellular compartments, suggesting that PRRSV induces apoptosis at late infection." (PMID 27310256, 2016). "In light of our data supporting VDAC1 blockade as central mediator of protection, we tested whether erastin or VBIT-4 substituted for ODN could protect against infection." (PMID 37695784, 2023). "In the present study, SVV infection induced VDAC1- and Bak/Bax-dependent mtDNA release, EV-A71 and FMDV infection induced VDAC1-dependent but Bak/Bax-independent mtDNA release, revealing multiple mtDNA release mechanisms arising from the infection of different picornaviruses." (PMID 36745686, 2023). "Likewise, after 3 h of infection, IEM data also showed that V antigen localized to mitochondria, marked by VDAC-1 (data not shown)." (PMID 19609450, 2009). "In addition, we observed that the VDAC1 mRNA levels did not change as a result of any of these treatments, while overexpression of SOD2 and OGG1 was shown to significantly increase each of the related mRNA levels, indicating successful infection." (PMID 33423158, 2021).
cardiovascular diseases (9 papers, 2017 to 2025). "VBIT-4 is a VDAC1 oligomerization inhibitor for the treatment of apoptosis-associated diseases such as neurodegenerative and cardiovascular diseases." (PMID 36816741, 2023). "It has also been proposed that the overexpression of VDAC1 in cardiovascular diseases, as well as in other diseases, is associated with mitochondrial dysfunction." (PMID 32271823, 2020). "Additionally, VDAC1 plays an important role in cardiovascular diseases, particularly in ischemia–reperfusion injury." (PMID 40285415, 2025). "Inhibiting the initiation of apoptosis at an early stage by inhibiting VDAC1 oligomerization may represent an effective approach to prevent or slow the enhanced apoptosis seen in neurodegenerative disorders and various cardiovascular diseases." (PMID 33114780, 2020).
metabolic disorders (5 papers, 2018 to 2026). "We confirmed that LINC01013 as a protein-binding scaffold connecting HSPA9 and VDAC1, contributing to the oligomerization of VDAC1 and mitochondrial dysfunction including oxidative stress and metabolic disorders, and ultimately hypoxic PH progression." (PMID 41491061, 2026).
movement disorder (2 papers, 2022). Neurological conditions resulting in abnormal voluntary or involuntary movement, which may impact the speed, fluency, quality and ease of movement. "These beneficial effects are corroborated by evidence that CBD changes the conductance of voltage-dependent anion channel 1, involved in the pathophysiology of movement disorders." (PMID 35629320, 2022).
myopathy (2 papers, 2022 to 2025). A disease of the muscle in which the muscle fibers do not function properly. "The expression of voltage dependent anion channel 1 (VDAC1), FUN14 domain containing 1 (FUNDC1), and translocase of outer mitochondrial membrane 20 (TOMM20) genes was not affected neither by the WB myopathy nor by the hypoxia exposure of primary myoblasts." (PMID 40034536, 2025). "Gene expression levels of mitochondrial ion transporters, including VDAC1,2,3, SLC25A4, and SLC25A6, were not significantly changed, though all appeared elevated in the myopathy-derived skin fibroblasts." (PMID 35216315, 2022).
bacterial infections (1 paper, 2024). "We also highlight the role of VDAC1 expression in various disease pathologies, including cardiovascular, neurodegenerative, and viral and bacterial infections, as explored through siRNA targeting VDAC1." (PMID 39456237, 2024).
inflammation (1 paper, 2024). Aberrant reaction of the microcirculation characterized by movement of fluid and leukocytes from the blood into extravascular tissues. "The results showed that VDAC1 knockdown in macrophages, like co‐administration of (+)3C‐20, significantly ameliorated alveolar pathology, increased survival rate, and suppressed acute lung inflammation in ALI mice." (PMID 39556713, 2024).
mitochondrial disease (1 paper, 2014). "Emerging research has revealed that VDAC1 may be also found in the plasma membrane in which it may represent a target for treatment of a range of conditions including neurodegenerative and mitochondrial diseases and possibly aging." (PMID 25470616, 2014).
VDAC1 also shares sentences with these, for which no sentence is quoted: Parkinson’s (4 papers); inflammatory bowel disease (3); peripheral neuropathy (3); adenocarcinoma (2); adrenocortical carcinoma (2); Arrhythmia (2); Batten disease (2); breast tumor (2); cervical intraepithelial neoplasia (2); clear cell Renal Cell Carcinoma (2); esophageal squamous cell carcinoma (2); heart disease (2); kidney disease (2); male infertility (2); neurological disease (2); pancreatic adenocarcinoma (2); renal carcinoma (2); skin cutaneous melanoma (2); Spinocerebellar ataxia (2); acute lung injury (1); acute myocardial infarction (1); acute promyelocytic leukemia (1); albinism (1); alcoholic liver diseases (1); B-cell lymphoma (1); behavioral disorders (1); bladder urothelial carcinoma (1); brain disease (1); cardiac arrhythmia (1); cervical tumor (1).
A further 60 diseases each share a sentence with VDAC1 in 1 paper.